ASPN (asporin)
Diseases named in the same sentence as ASPN in open-access papers (continued):
Sharing a sentence is not in itself a finding about the gene and the disease.
cancer (continued). "In this review, we seek to elucidate the signaling pathways and functions regulated by asporin in different types of cancer and to highlight some important issues that require investigation in future research." (PMID 31608236, 2019). "Here we gave an alternative explanation of ASPN’s pro-motility role in cancer cells, i.e. activation of TGF-β/Smad2/3 signaling from inside cells." (PMID 30728352, 2019). "In many tumors the cancer-specific matrix also includes increased ASPN and DCN, due to their induction by e.g. TGFβ or stiff matrix." (PMID 29176937, 2017). "Asporin can also be found in gene lists from other expression microarray analyses both in breast and other cancer types." (PMID 27409832, 2016). "The results evidenced a 3-fold, significant (p = 0.002) increase in the number of cancer cells present in the lung tissue of the control mice compared to the mice with asporin-overexpressing NBFs." (PMID 26327350, 2015). "However, our scRNA-seq confirmed that accurate ASPN expression was observed predominantly in pericytes, suggesting that interactions of ASPN were performed between pericytes and cancer cells in clinical GC tumors." (PMID 40075643, 2025). "ASPN is highly expressed by CAFs and plays important roles in cancer progression." (PMID 36358747, 2022). "In addition, studies have shown that ASPN is enriched in CAFs and can promote cancer cell metastasis via regulating cell metabolism." (PMID 35462906, 2022). "Taken together, ASPN may function as a key molecule in CEFs that influences cancer cell dissemination, suppression of CD8+ T cells, and regulation of IGF‐I signaling." (PMID 34379869, 2022). "A growing body of evidence now demonstrates that asporin acts as an extracellular matrix component or intracellular protein that positively or negatively controls proliferation, invasion, and metastasis of cancer cells by regulating the TGF-β, EGFR, and CD44 signaling pathways." (PMID 35600399, 2022). "Sasaki and co-workers recently suggested that asporin expression could reprogram cancer cells to acquire resistance to oxidative stress." (PMID 35631574, 2022). "The present study revealed that ASPN may play a central role in CEFs, which promote cancer cell dissemination, T‐cell suppression, and insulin growth factor (IGF)‐I signaling." (PMID 34379869, 2022). "Studies have elicited that FAP-expressing CAFs can demonstrate tumor-forming functions in some cancers such as gastric cancer, but also asporin-expressing CAFs were found to inhibit cancer development in breast cancer, offering two different opportunities for therapeutic intervention." (PMID 33808627, 2021). "We hypothesized that enhanced expression of ASPN in GC potentially affects cancer cell migration through activation of EMT." (PMID 34379688, 2021). "Therefore, here, we seek to elucidate the signaling pathways and different functions regulated by asporin in different types of cancer and to highlight some important issues that still need to be investigated." (PMID 31608236, 2019). "Whether asporin could interact with these proteins and regulate the corresponding signaling pathways in cancer needs to be investigated in the future." (PMID 31608236, 2019). "Subcellular localization of ASPN in the cytoplasm, even in the nucleus, was also observed in many other studies, but its exact biological function inside cancer cells was totally unknown." (PMID 30728352, 2019). "Over the past decade, ASPN has emerged as a potential biomarker for various types of cancer." (PMID 30728352, 2019). "Therefore, we will narrow the focus of this review to asporin, simply describing its sequence, structure, and functions, and primarily highlighting its multifaceted roles in cancers." (PMID 31608236, 2019). "Overexpression of ASPN has been identified in breast, prostate, gastric, and pancreas cancers." (PMID 30728352, 2019). "Interestingly, Hs578T and SNB-75 cancer cells with asporin expression have the highest expression of smooth muscle actin." (PMID 27409832, 2016).
cancer (continued). "Our results showed that ASPN was upregulated and annotated in cancer function." (PMID 24982892, 2014). "Thus, the intracellular function of asporin in cancer and whether asporin subcellular localization is controlled by its post-translational modifications, still needs to be investigated." (PMID 31608236, 2019). "In the current study, we aimed to explore asporin, a member of the class I SLRP family, which is at present insufficiently researched in cancer." (PMID 26327350, 2015). "In GC, Asporin (ASPN), a small leucine-rich proteoglycan (SLRP), was reported to be predominantly expressed in CAFs and plays essential roles in promoting co-invasion of CAFs with cancer cells." (PMID 40075643, 2025). "Although biglycan, asporin and decorin (key constituents of the bone ECM) belong to the class I SLRP, they possess both pro- and anti-tumorigenic potential and have different roles in the pathogenesis of different cancers." (PMID 36765749, 2023). "ASPN further induced expression of IDO‐1, KYNU, and PAPP‐A in CEFs, leading to cancer cell dissemination, CD8+ T‐cell cytotoxicity, and activation of IGF‐I signaling in cancer cells." (PMID 34379869, 2022). "Cytoplasmic ASPN interacts with Smad2/3 to promote its translocation to the nucleus and activates the TGF-β/Smad2/3 signaling pathway to promote EMT and proliferation in various cancer cells." (PMID 36011263, 2022). "We also noted a change in the expression level of 3 genes (PDGFRB, EMILIN1 and ASPN) during cultivation of the primary cell line of skin fibroblasts in the absence of cancer cells for 4 weeks." (PMID 36263012, 2022). "Moreover, ASPN upregulates CD44 expression and activates Rac1 via interaction with CD44 on the cell membrane, which also increases cancer cell spreading." (PMID 34379869, 2022). "This was the first study to show the function of asporin as an intracellular molecule and not as an extracellular matrix component in cancer." (PMID 31608236, 2019). "Previous studies revealed that Asporin (ASPN) is a potential mediator in the development of various types of cancer as a secreted stroma protein, but the function of ASPN inside the cancer cells remains largely unknown." (PMID 30728352, 2019). "The current study underscores the limited expression of asporin in normal adult tissue, qualifying it also as a target for antibody drug conjugates, and highlights its ability to inhibit TGF-β1 downstream signaling, cancer cell migration, and EMT." (PMID 26327350, 2015). "Strong asporin expression was detectable in the stroma of the cancer lesions, with epithelial cancer cells being negative for asporin expression." (PMID 26327350, 2015). "CAFs isolated from HR+ tumors expressed high levels of asporin, which they were able to maintain in vitro (for several weeks) without the need to be in contact with cancer cells." (PMID 26327350, 2015). "The STRING analysis of ASPN in Canis lupus familiaris (accessed 10.03.2025) in the present study revealed its co-expression with periostin (POSTN), a secreted extracellular matrix protein involved in cancer stem cell maintenance and the metastatic progression of cancers." (PMID 40566602, 2025). "Interestingly, ASPN and THY1 have both been shown to impact cancer stem cells." (PMID 33600062, 2021). "ASPN+THY1− cells were not significantly enriched in the stroma adjacent to cancer." (PMID 33600062, 2021). "In this study we report two candidate genes, asporin (ASPN) and collagen triple helix repeat containing 1 (CTHRC1), which might be significant in mammary gland carcinogenesis and may also be important either in cancer diagnosis or therapy." (PMID 17389037, 2007). "Interestingly, P-DXd shows in vitro and in vivo efficacy, even in the presence of Aspn+ cancer-associated stromal cells, suggesting that P-DXd may have a higher affinity to HER3 than ASPN or the P-DXd binding epitope is not obstructed by ASPN binding." (PMID 40857406, 2025).
cancer (continued). "Furthermore, differentially quantified proteins (such as PGS2, UGDH, ASPN, LUM, COEA1, and PRELP) were found in comparisons of healthy and cancer breast tissues, suggesting potential utility of the All-in-One pipeline for the emerging application of proteomic cancer sub-typing." (PMID 36937585, 2023). "Recombinant ASPN induced expression of KYNU and IDO‐1 within several hours in NFs, while they were not induced by CM derived from at least other two cancer cells." (PMID 34379869, 2022). "Through the SAM calculation process, ACTA1, ASPN, C4orf7, CYP26B1, and PRAME showed statistically significant differences in expressions between early and late stages of cancer in both Asian and non-Asian samples." (PMID 24982892, 2014).
cardiovascular disease (2 papers, 2020 to 2022). "Nevertheless, to our knowledge, only a few studies have found an alteration in ASPN gene expression in the context of cardiovascular diseases." (PMID 32670412, 2020).
heart disease (1 paper, 2020). "Following those studies, we have identified ASPN as one of the most significant genes altered in heart disease, since it was found among the highest fold change cutoff used and prominent in the PPI network." (PMID 32670412, 2020).
infection (1 paper, 2022). The state of being infected such as from the introduction of a foreign agent such as serum, vaccine, antigenic substance or organism. "The greatest decrease in expression 24 h after infection was observed for the gene encoding asporin (ASPN) (−4.52)." (PMID 35746747, 2022).
ASPN also shares sentences with these, for which no sentence is quoted: Duchenne muscular dystrophy (3 papers); knee osteoarthritis (3); genetic disorders (2); glioblastoma (2); lung carcinoma (2); prostate adenocarcinoma (2); angiosarcoma (1); bladder cancer (1); bone and joint diseases (1); colon cancer (1); connective tissue diseases (1); degenerative diseases (1); developmental dysplasia of the hip (1); endometrial cancer (1); gall bladder cancer (1); glioma (1); hand osteoarthritis (1); head and neck cancer (1); hepatocellular carcinoma (1); Hyperglycemia (1); hypertrophic cardiomyopathy (1); idiopathic pulmonary fibrosis (1); invasive lobular carcinomas (1); ischemic cardiomyopathy (1); kidney tumors (1); liver cancer (1); melanoma (1); metabolic disorder (1); non-small cell lung carcinoma (1); otosclerosis (1).
A further 5 diseases each share a sentence with ASPN in 1 paper.